TNF (tumor necrosis factor)
Diseases named in the same sentence as TNF in open-access papers (continued):
Sharing a sentence is not in itself a finding about the gene and the disease.
septic peritonitis (6 papers, 2017 to 2022). Septic peritonitis is an inflammatory condition of the peritoneum that occurs secondary to microbial contamination. "Septic peritonitis induced significant impairment of learning memory and exploratory activity, which was associated with a higher expression of IL-17A, IL-1β, and TNF-α in the brain homogenate." (PMID 31686986, 2019). "Mice challenged with septic peritonitis had significantly higher plasma levels of TNF-α, IL-6, IL-10, and IFN-γ compared to the sham-operated mice." (PMID 34366711, 2021). "In the present study, we found that septic peritonitis induced a significant increase in IL-17A, IL-1β, and TNF-α in brain homogenate, and the enhanced inflammation was strongly associated with the deterioration in cognitive functions and exploratory activity." (PMID 31686986, 2019). "To get insight into the influence of gzmA and gzmB deficiency on the local inflammatory response elicited during septic peritonitis, we measured proinflammatory (TNF-α, IFN-γ, and IL-1β, IL-6) and anti-inflammatory (IL-10) cytokines as well as MCP-1 and KC levels in PLF." (PMID 28694562, 2017). "In an LPS-induced septic peritonitis mouse model, direct stimulation of the cervical vagus could significantly decrease the expression level of proinflammatory factors such as TNF-α in the serum, heart and liver, suggesting its anti-inflammatory and immunoregulatory functions." (PMID 36058917, 2022).
severe combined immunodeficiency (6 papers, 2009 to 2025). Severe combined immunodeficiency (SCID) comprises a group of rare monogenic primary immunodeficiency disorders characterized by a lack of functional peripheral T lymphocytes resulting in early-onset severe respiratory infections and failure to thrive. "This lack of antibody response can be attributed to the diagnosis of the PID patient (nude severe combined immunodeficiency) and the ongoing therapeutic regimen for the HSCT patient, which involves corticosteroid administration and anti-TNF therapy with adalimumab." (PMID 41280926, 2025).
sexual dysfunction (6 papers, 2015 to 2025). Disturbances in sexual desire and the psychophysiologic changes that characterize the sexual response cycle and cause marked distress and interpersonal difficulty. "Firstly, hormonal and inflammatory responses induced by the fatty cell-secreted cytokine factors (i.e. TNF-alpha, IL-6and leptin) may contribute to the onset of sexual dysfunction." (PMID 32299459, 2020). "Whether TNF-α can be a treatment alternative or protection of sST2 activation in such cases of sexual dysfunction remains to be established." (PMID 25615941, 2015). "TNF-α can play an important role in cardiovascular disease, mainly because of its direct effects on the vasculature, and may also be involved in sexual dysfunction." (PMID 25615941, 2015). "In addition, a pilot study demonstrated that anti-TNF-α therapy may improve sexual dysfunction in male AS patients." (PMID 25780459, 2015).
sialadenitis (6 papers, 2009 to 2025). Sialadenitis is an infection of the salivary glands. "Both TNF-α and IL-6 have been implicated in inflammatory salivary gland diseases such as Sjogren's disease and irradiation-induced sialadenitis." (PMID 39813519, 2025). "In this experiment, we treated organoids with TNF-α to mimic the inflammatory condition in human salivary glands recognized in sialadenitis and analyzed the pathophysiological changes using the CCh- and forskolin-induced swelling assays." (PMID 32801121, 2020). "In inflammatory conditions like sialadenitis, in general, pro-inflammatory cytokines such as tumor necrosis factor-α (TNF-α, also known as TNF) are upregulated, but their function is still unclear." (PMID 32801121, 2020). "Lastly, a mouse model that overexpresses TNFα in salivary tissue specifically develops robust sialadenitis reminiscent of that seen in SS patients." (PMID 31993047, 2019). "Interestingly, blockade of TNF has recently been reported to attenuate lymphocyte responses in Sjögren’s-like sialadenitis and other pathologies, pointing to indirect effects of this cytokine on these adaptive immune cells." (PMID 33679695, 2020). "Consequently, the previously reported beneficial effects of pharmacological TNF blockade on salivary gland function in autoimmune Sjögren’s-like sialadenitis might be—at least in part—due to interference with these TNF-dependent microvascular processes." (PMID 33679695, 2020).
spinal cord ischemia (6 papers, 2013 to 2025). Reduced blood flow to the spinal cord which is supplied by the anterior spinal artery and the paired posterior spinal arteries. "Spinal cord ischemia/reperfusion injury appears contingent on oxygen-derived free radical damage, mitochondria-dependant apoptosis, TNF-α production, and specific phospholipid signaling cascades resulting in neuronal injury in human and animal models." (PMID 23533882, 2013). "Additionally, some studies showed that IL-4 and IL-13 suppressed the expression and production of pro-inflammatory cytokines (TNF-α and IL-1β) in the spinal cord of animal models of spinal cord ischemia." (PMID 34679060, 2021).
spinal stenosis (6 papers, 2014 to 2024). Narrowing of the spinal canal. "Ossification of the ligamentum flavum is the main cause of spinal stenosis, and TNF not only promotes the proliferation of primary cells of the thoracic ossification of the ligamentum flavum but also enhances osteoblast differentiation to promote SCS onset." (PMID 38895179, 2024). "Increased expression of TNF is associated with osteogenesis of the LF, which contributes to spinal stenosis." (PMID 36036007, 2022).
staphylococcal infection (6 papers, 2011 to 2025). An infection caused by Staphylococcus. "PTX protects rodents from acute lung injury induced by E. coli and staphylococcal infection, endotoxin, and TNF-α." (PMID 37107001, 2023). "During staphylococcal encounter with murine neutrophils or staphylococcal infection of the murine peritoneal cavity, calprotectin increases the activity of the SaeRS TCS as well as the production of proinflammatory cytokines such as IL-1β and TNF-α, resulting in higher murine mortality." (PMID 26147796, 2015).
sweet syndrome (6 papers, 2019 to 2023). "Occurrence of Sweet syndrome is possible during anti-TNF-α treatment although it can also be effective in pre-existing Sweet syndrome." (PMID 31440261, 2019).
Thromboembolism (6 papers, 2010 to 2026). The formation of a blood clot inside a blood vessel that subsequently travels through the blood stream from the site where it formed to another location in the body, generally leading to vascular occlusion at the distant site. "Several studies have reported that PM exposure enhances interleukin-6 (IL-6) and tumor necrotic factor-α (TNF-α) activation, contributing to the inflammatory process and resulting in thromboembolism." (PMID 39091522, 2024). "Although the role of aPLs in the development of thromboembolism in our patients is uncertain, the potential complications of anti-TNF therapy should be remembered in order to prevent, detect, and manage thrombotic events." (PMID 20157435, 2010).
tonsillitis (6 papers, 2017 to 2024). Inflammation of the tonsillar tissue. "Other factors that may contribute to or worsen PPP include infections (such as tonsillitis and dental infections), psychological stress, and certain medications like TNF and IL-17 inhibitors, which could also trigger PPP." (PMID 39568752, 2024). "Although salivary levels of IL-6, IL-33 and TNF-α were significantly increased in patients with recurrent tonsillitis compared to healthy controls, these parameters were unable to differentiate between the diagnosis groups since significance was only achieved through single outliers." (PMID 34187480, 2021). "They rarely observed IL1β and TNF-α in the recurrent tonsillitis group." (PMID 30213594, 2020).
toxicity (6 papers, 2012 to 2024). The degree to which an agent can damage an organism. "Elevated TNF-α secretion is considered a major determinant of susceptibility to ethanol-induced liver toxicity." (PMID 37627597, 2023). "This activity was also reported in a rat model of titanium-dioxide-induced kidney toxicity, where idebenone reduced the levels of interleukins 1, 6 (IL-1, IL-6) and tumor necrosis factor alpha (TNF-α), which was associated with improved kidney function." (PMID 32998266, 2020). "Like our results, cocoa exhibited anti-inflammatory activity by reducing inflammatory TNF-α in alcohol-induced liver toxicity models in rats." (PMID 37631278, 2023). "In conclusion, DOXO-induced heart toxicity displayed a marked lowering in HW/BW ratio, significant elevations in the activities of CPK, AST, and LDH enzymes, significant elevations in Na, K, TNF-α, IL-10, MDA, and NO levels, and significant drops in levels of GSH and SOD." (PMID 36967438, 2023).
tubulointerstitial nephritis (6 papers, 2014 to 2025). "Tubulointerstitial nephritis (TIN) in patients with IBD has been associated with exposure to 5-aminosalicylates (5-ASA), cyclosporine A, tumor necrosis factor-alpha (TNF-α) inhibitors and vedolizumab." (PMID 39421866, 2024). "Egr-1 deficiency in primary renal tubuloepithelial cells isolated from mice could weakly respond to pro-inflammatory and pro-fibrotic stimuli ex vivo, and Egr1−/− mice with tubulointerstitial nephritis expressed less TNFα and CCL2." (PMID 38397780, 2024). "In a model of tubulointerstitial nephritis, CCL3 and CCR5 knockout animals demonstrated better renal histology, less inflammatory infiltration, lower levels of serum creatinine, and reduced expression of KIM-1, TNF-α, and collagen in the renal tissue." (PMID 32961903, 2020).
Vestibular schwannoma (6 papers, 2017 to 2025). A vestibular schwannoma (also known as acoustic neuroma, acoustic neurinoma, or acoustic neurilemoma) is a benign, usually slow-growing tumor that develops from the VIIIth cranial nerve supplying the inner ear. "Therefore, the transient suppression of TNFα expression by RNAi may be more desirable when aiming to prevent hearing loss secondary to ototoxic secretions from vestibular schwannomas or other autoimmune etiologies." (PMID 29018206, 2017). "Human studies that compared perilymph from healthy patients and patients with vestibular schwannoma found specific elements of the tumor such as TNF-α, a pro-inflammatory cytokine, notably accountable for SNHL in these tumors." (PMID 38928621, 2024). "Current evidence indicates that vestibular schwannomas may damage the sensory epithelia of the inner ear through tumour-secreted factors, including tumour necrosis factor alpha (TNFα)." (PMID 37195449, 2023). "Having established that iRGD-targeted delivery of siRNA can lead to receptor- and sequence-specific suppression of TNFα gene expression in an NF2-derived vestibular schwannoma cell line, we then evaluated the ability of iRGD nanoparticles to mediate RNAi in primary human VS cultures." (PMID 29018206, 2017).
vitamin deficiency (6 papers, 2018 to 2025). A disorder that is caused by the deficiency of a vitamin. "TNF-α levels are increased in HIV patients due to the status of immune hyperactivation and may be the cause of hypovitaminosis D in such individuals." (PMID 34835029, 2021). "However, no other vitamin deficiency, even concurrent folate/B12, significantly altered TNF-α expression." (PMID 36678131, 2023).
Achalasia (5 papers, 2019 to 2025). A disorder of esophageal motility characterized by the inability of the lower esophageal sphincter to relax during swallowing and by inadequate or lacking peristalsis in the lower half of the body of the esophagus. "We also found many pro-inflammatory factors in expanded effector T cells and effector memory T cells that were more highly expressed in achalasia than in controls, including TNF, IFNG, GZMB, and GZMH." (PMID 37542039, 2023). "Elevated IFN-γ and low levels of TNF-α are seen in chagasic mega-esophagus, a process similar to achalasia, compared to controls." (PMID 30744559, 2019). "In their study, levels of interleukin-12 (IL-12) (p = .031) and TNF-α (p = .026) were significantly elevated in the achalasia group compared to the controls." (PMID 30744559, 2019). "However, several cytotoxic enzymes and inflammatory cytokines, including GZMA, GZMB, GZMK, GNLY, and TNF were downregulated in TRM in achalasia, consistent with a previous study of TRM in MS42." (PMID 37542039, 2023). "A review of the literature suggests that TNF-α, IL-6, IFN-γ, IL-12, IL-17, IL-22, and IL-23 theoretically could contribute to the underlying etiology of achalasia." (PMID 30744559, 2019). "Another study compared the plasma immunological profiles of TNF-α, IL-6, IFN-γ, IL-12, IL-17, IL-22 and IL-23 in 53 patients with achalasia, 22 eosinophilic esophagitis (EoE), and 20 gastroesophageal reflux disease, through Quantikine Human Immunoassays." (PMID 39337632, 2024). "The primary aim of our study was to compare the plasma immunological profiles of plasma of TNF-α, IL-6, IFN-γ, IL-12, IL-17, IL-22, and IL-23 in patients with achalasia, EoE, and GERD." (PMID 30744559, 2019). "In this study, we investigated plasma biomarker levels of IL-6, IL-12p70, IL-17, IL-22, IL-23, TNFα and INF-γ in patients with achalasia, EoE, and GERD." (PMID 30744559, 2019).
Acute otitis media (5 papers, 2011 to 2024). Acute otitis media is a short and generally painful infection of the middle ear. "In children, elevated cytokine levels of CXCL8 and TNF have been associated with positive cultures for S. pneumoniae in NP during acute otitis media." (PMID 38271409, 2024).
acute pharyngitis (5 papers, 2020 to 2025). An acute and painful inflammatory process that affects the pharynx. "In order to assess the impact of TR on the inflammatory response in AP rats, inflammatory cytokines closely associated with acute pharyngitis, such as TNF-α and IL-6, were measured." (PMID 39568590, 2024). "IL-6 activates mononuclear macrophages and impacts immune responses, whereas IL-1β overexpression causes tissue damage, edema, and exacerbate responses in rats with acute pharyngitis through interactions with TNF-α and IL-6." (PMID 41357871, 2025). "In support, a recent study applying a rabbit model of acute pharyngitis revealed that the anti-inflammatory effects of resveratrol were due to down-regulated caspase-3 expression and decreased IL-6 and TNF-α serum levels." (PMID 33255723, 2020). "It was experimentally confirmed that G. szechenyii extracts had ameliorative effects on ammonia-induced acute pharyngitis model in rats, and its mechanism of action may be related to the reduction of TNF-α, IL-1β, and IL-6 levels." (PMID 38161696, 2023). "Subsequently, the mRNA expressions of IL-6, TNF-α, and COX-2 were evaluated in the pharyngeal tissue of acute pharyngitis rats." (PMID 39568590, 2024). "Our initial exploration revealed that TR treatment for acute pharyngitis engages targets such as PIK3CA, IL6, AKT1, TNF, PTGS2/COX-2, among others." (PMID 39568590, 2024). "Moreover, Resveratrol showed potent anti-inflammatory activity as lowered NF-κB, TNF-α, and IL-6 serum levels, as well as COX-2 activity and reactive oxygen species production in an animal model of acute pharyngitis." (PMID 32423112, 2020).
Adrenal insufficiency (5 papers, 2013 to 2025). Insufficient production of steroid hormones (primarily cortisol) by the adrenal glands. "Secondary adrenal insufficiency impairs cortisol-mediated suppression of inflammatory cytokines and immune regulation, allowing IL-6 and TNF-α to remain elevated, further accelerating skeletal muscle protein breakdown." (PMID 41181767, 2025). "SND increased overall survival rate within 4 days and attenuated adrenal insufficiency in septic rats by downregulating TLR4 mRNA and protein expression in adrenal tissue, inhibiting adrenal production of TNF-α and IL-10, and improving adrenal responsiveness." (PMID 30018657, 2018).
advanced heart failure (5 papers, 2022 to 2025). Patients with advanced heart failure have severe limitations, experiences symptoms even while at rest and are mostly bedbound patients. "Biologic drugs have different mechanisms of action, and, except for anti-TNF-α agents, which depress cardiac muscle function and are contraindicated in advanced heart failure, they benefit overall cardiovascular risk." (PMID 40277935, 2025). "Meanwhile, the absence of TNF-α reduced the inflammatory response and cardiac fibrosis in mice, and TNF-α inhibition has been shown to improve left ventricular structure and function in patients with advanced heart failure." (PMID 36015225, 2022). "High plasma levels of chronically elevated pro-inflammatory cytokines, such as tumor necrosis factor (TNF), are known to be related to cardiac cachexia in advanced heart failure." (PMID 38337428, 2024).
age-related hearing loss (5 papers, 2019 to 2025). "SSNHL and age-related hearing loss may be associated with inflammation-related genetic factors, including interleukins, heat shock proteins, and tumor necrosis factor (TNF)." (PMID 34865658, 2021). "In addition, increased expression of TNF-α has been observed in the modiolus, spiral ganglion, and stria vascularis in mouse models of presbycusis, and other groups have shown that vibration-induced SNHL results in upregulation of intracochlear levels of TNF-α." (PMID 32116980, 2019).
aortic atherosclerosis (5 papers, 2019 to 2023). A atherosclerosis that involves the aorta. "After aortic chemerin gene was inhibited by adenovirus, aortic atherosclerosis induced by high-fat diet was significantly meliorated, serum levels of TNF-α and IL-1β decreased, mRNA and protein levels of NF-κBp65, PCNA, p-p38-MAPK, p-JNK, and p-ERK 1/2 decreased simultaneously." (PMID 31781638, 2019).
Aortic dissection (5 papers, 2019 to 2025). Aortic dissection refers to a tear in the intimal layer of the aorta causing a separation between the intima and the medial layers of the aorta. "These inflammatory mediators (IL-6 and TNF-α), along with proteases like matrix metalloproteinases (MMPs), can disrupt the structural integrity of the aortic wall, thus increasing the risk of aortic dissection progression." (PMID 41567381, 2025). "While we did not observe relevant differences in TNF-α plasma levels between chronic and acute aortic dissections, inflammation could be focused on intramural areas and therefore not be reliably detectable using plasma measurements." (PMID 39501015, 2024).
Apnea (5 papers, 2015 to 2025). Lack of breathing with no movement of the respiratory muscles and no exchange of air in the lungs. "In another study, the TNF-α values in the uvula tissue of individuals with apnea were found to be high." (PMID 37062544, 2023). "Therefore, the increased levels of cytokines (i.e., IL-6 and TNF-alpha) that activate nuclear factor kappa B and the releasing of free fatty acids by excess adipose tissue might be involved in the pathogenic mechanisms leading to apnea in humans." (PMID 25760760, 2015). "Interestingly, TNFα is elevated in patients with sleep apnoea (in the absence of any concomitant rheumatological diagnosis), and continuous positive airway pressure has been shown to decrease soluble TNF in this setting." (PMID 34825268, 2022).
arrhythmogenic right ventricular cardiomyopathy (5 papers, 2018 to 2025). "The most significantly enriched of these pathways included the TNF, PI3K-Akt, HIF-1, Rap1, Hippo, ECM-receptor interaction, and arrhythmogenic right ventricular cardiomyopathy (ARVC) signaling pathways." (PMID 33711974, 2021).